STAT3 (signal transducer and activator of transcription 3)
Diseases named in the same sentence as STAT3 in open-access papers (continued):
Sharing a sentence is not in itself a finding about the gene and the disease.
ovarian carcinoma (continued). "STAT3 phosphorylation measurements were downloaded and analyzed from the TCGA ovarian cancer dataset in which STAT3 pY705 was quantified using the Reverse Phase Protein Array (RPPA) platform." (PMID 31534498, 2019). "Our data demonstrated that KO of STAT3 resulted in reduced tumor growth in both 2D and 3D cell culture models and in xenograft models of ovarian cancer." (PMID 31534498, 2019). "We observed suppressed cell migration, spheroid formation and tumor growth (both in vitro and in vivo) in STAT3 KO ovarian cancer cells." (PMID 31534498, 2019). "The adipokines secreted from omental adipocytes activate pro-survival pathway, p38, and signal transducer and activator of transcription 3 (STAT3) in ovarian cancer cells." (PMID 31334678, 2019). "Since STAT3 has been shown to be necessary for migration and invasion 23, we confirmed that KO of STAT3 altered the migratory ability of ovarian cancer cell lines in an in vitro wound-healing assay." (PMID 31534498, 2019). "A previous study showed that IL-6 has the ability to induce apoptosis in many human ovarian cancer developments by blocking the IL-6R/STAT3 pathway." (PMID 31783838, 2019). "Curcumin analogues, such as HO-3867, which belong to the diarylidenyl piperidin-4-ones (DAP) family of anti-cancer agents that suppress cellular growth and metastasis by targeting STAT3 in ovarian cancer cells." (PMID 31766284, 2019). "Together, these results suggest that the dual inhibition of JAK2/STAT3 and AKT demonstrates striking antitumor effect in ovarian cancer cells with PIK3R1 loss." (PMID 30755611, 2019). "More importantly, the blockade of STAT3 phosphorylation with a JAK 2 inhibitor significantly reduced ovarian cancer metastasis in an established genetic mouse model of ovarian cancer." (PMID 31261739, 2019). "Having established that PIK3R1 loss activates STAT3 and AKT pathways in ovarian cancer cells, we reasoned that cells with PIK3R1 loss would be sensitive to inhibitors of these two pathways." (PMID 30755611, 2019). "STAT3 was constitutively activated at Tyr 705 in cancer cells derived from ovarian cancer patient ascites, resulting in platinum-based chemoresistance." (PMID 31597912, 2019). "To determine the in vivo effects of STAT3 on ovarian cancer tumorigenesis and metastasis, we performed animal assays with cells expressing STAT3-CA, STAT3-WT, and STAT3-DN along with those expressing empty vector." (PMID 31597912, 2019). "In summary, we defined the mechanism that mediates the crosstalk between Notch and STAT3 pathways in platinum‐resistant ovarian cancer and determined its functional relevance." (PMID 30993885, 2019). "Our study provides a rich, multi-faceted summary of the molecular mechanisms impacted by STAT3 inhibition and will further guide the evaluation of STAT3 as a therapeutic target in ovarian cancer." (PMID 31534498, 2019). "The present study provides independent evidence that miR-34a regulates the IL-6R/STAT3 pathway in ovarian cancer by demonstrating that IL-6R reexpression is able to mitigate the effects of miR-34a mimetic oligos." (PMID 31448054, 2019). "Positively charged Chitosan oligosaccharide (CSO) was added to the STAT3 siRNA-PLGA micelles and the micelles showed high efficiencies of cellular uptake and STAT3 gene silencing in SKOV3 ovarian cancer cells." (PMID 30847297, 2019). "A total of four ovarian cancer STAT3 KO single cell clones were generated from HEY, OVCAR3, OVCAR8 and SKOV3." (PMID 31534498, 2019). "ORA DAVID revealed 3 common gene sets, 2 of which were related to the extracellular matrix reinforcing STAT3's functional relevance to cell adhesion and migration in ovarian cancer." (PMID 31534498, 2019). "This study for the first time showed enhanced STAT3 phosphorylation upon the addition of exogenous Gal‐3 to ovarian cancer cells." (PMID 31197964, 2019). "We identified that the transcription and expression of STAT1 is increased in STAT3 KO ovarian cancer cells." (PMID 31534498, 2019).
ovarian carcinoma (continued). "To examine the basal proliferation ability of ovarian cancer cell lines with different levels of STAT3 activation, we first detected the cell viability by MTT assay." (PMID 31597912, 2019). "As an oncogenic factor, miR551b-3p was shown to upregulate STAT3 (Signal transducer and activator of transcription 3) protein levels, contributing to resistance to apoptosis, higher rates of survival, and increased cell proliferation in ovarian cancer." (PMID 31137914, 2019). "Interference of STAT3 activity has been employed as a strategy to hinder ovarian cancer cell proliferation." (PMID 31861720, 2019). "STAT3 KO significantly reduced tumor growth in all ovarian cancer cell-derived xenografts compared to WT control." (PMID 31534498, 2019). "Melittin induced apoptosis of human ovarian cancer cells via increase of death receptor expression and inhibition of signal transducer and activator of transcription 3 (STAT3) pathway." (PMID 30866426, 2019). "In this study, a combination of CRISPR-Cas9-mediated gene KO and multi-omic genome-wide profiling enabled us to identify multi-level (Bru-Seq, RNA-Seq, and MS Proteomic) expression signatures of parental and STAT3 KO ovarian cancer cells." (PMID 31534498, 2019). "Non-toxic cationic solid lipid nanoparticles (SLN) was combined with STAT3 decoy oligodeoxynucleotides (ODN) to treat human ovarian cancer cells and cellular uptake of SLN-decoy ODN was comparable to that of Lipo-decoy ODN which is more toxic." (PMID 30847297, 2019). "A recent study reported that over-expression of ALDH1A2 decreased cell growth and migration by down regulating STAT3 activation in ovarian cancer cells." (PMID 31534498, 2019). "In vitro and in vivo studies with ovarian cancer cell lines have shown that siRNA and shRNA mediated STAT3 depletion, downregulated the expression of Cyclin D1, Survivin as well as reduced tumor weight." (PMID 31861720, 2019). "It demonstrated that 20(S)-Rg3 inhibited the Warburg effect by targeting STAT3/HK2 pathway in ovarian cancer cells." (PMID 30514289, 2018). "Activated STAT3 is over-expressed in a majority of Paclitaxel-resistant ovarian cancer cells and tumor tissues, and thus represents an important target for anti-tumor therapies." (PMID 30127274, 2018). "To elucidate the underlying mechanism of miR-216a in ovarian cancer regulation, we also demonstrated that STAT3, a putative oncogene in ovarian cancer, is a regulator of miR-216a." (PMID 30061175, 2018). "CAFs activate STAT3 signaling in ovarian cancer cells resulting in the development of chemoresistance through the increased expression of the antiapoptotic survivin and Bcl-2." (PMID 30380628, 2018). "A number of signaling pathways, including MAPK/ERK, PI3K/AKT and JAK/STAT3 pathways, are constitutively activated and play important roles in the growth and progression of ovarian cancer." (PMID 29849942, 2018). "More recently, an increase in the activation of STAT3 following hypoxia is shown to be at least partly responsible for mediating chemoresistance in the human ovarian cancer (i.e., A270 cells) and TNBC (i.e., MDA-MB-231 cells)." (PMID 30347860, 2018). "Knockdown of STAT3 enhanced cisplatin-induced apoptosis in ovarian cancer and non-small cell lung cancer cells." (PMID 30473665, 2018). "We demonstrate that paclitaxel treatment enhanced JAK2/STAT3 activation which resulted in the enrichment of cancer stem cell (CSC)-like phenotype in the surviving ovarian cancer cells in vitro and in in vivo mouse xenografts." (PMID 29682172, 2018). "Several recent studies have demonstrated a critical role of STAT3 in ovarian cancer growth and progression." (PMID 29849942, 2018). "NO has been shown to inhibit STAT3 activation in ovarian cancer cells and endothelial NO bioavailability is commonly lost in hypertension and related diseases." (PMID 29800237, 2018).
ovarian carcinoma (continued). "Taken together, our results demonstrated that blocking JAK/STAT3 pathway can synergistically enhance anti-tumor activity of paclitaxel in ovarian cancer cells." (PMID 29849942, 2018). "The poor prognosis in ovarian cancer patients with higher STAT3 expression was in line with the data from Kaplan–Meier plotter analysis." (PMID 29423040, 2018). "Previous studies have shown that constitutive activation of STAT3 confers resistance to platinum and paclitaxel induced apoptosis in ovarian cancer." (PMID 29849942, 2018). "It has been previously demonstrated that inhibition of STAT3 pathway effectively suppresses ovarian cancer growth and progression." (PMID 29986501, 2018). "A growing body of evidence has demonstrated the promising anti-tumor effects of resveratrol in ovarian cancer cells, including its inhibitory effects on STAT3 activation." (PMID 29986501, 2018). "We show that ruxolitinib inhibits STAT3 activation and ovarian tumor growth both in ovarian cancer cells and in an ovarian cancer mouse model." (PMID 29849942, 2018). "In conclusion, intracellular Sp17 expression identified a sub-population of ID8 ovarian cancer cells with tumor-forming potential, which display increased expression of PD-L1 and STAT3." (PMID 30127274, 2018). "Both leptin and OB3 stimulated the phosphorylation of STAT3, but only leptin promoted the proliferation of ovarian cancer cells." (PMID 28750624, 2017). "It has been previously reported that STAT3 was phosphorylated at Tyr705 in epithelial ovarian cancer cells." (PMID 28859117, 2017). "We performed immunoblotting assay and didn't observe the phosphorylation level change of both AKT and STAT3 in ovarian cancer cells upon treatment with NO donor or NOS inhibitor." (PMID 28380434, 2017). "IL-6-STAT3 signaling axis has been shown to be relevant to pathogenesis of ovarian cancer, with phosphorylation/activation and subsequent nuclear translocation of STAT3 being frequent events in ovarian cancers, resulting in poor prognosis." (PMID 28859117, 2017). "A recent study has shown that induction of ER stress modulates signal transducer and activator of transcription 3 (STAT3) activity and causes apoptosis in ovarian cancer cells." (PMID 29254150, 2017). "YSY01A also enhances cisplatin cytotoxicity in cisplatin-resistant ovarian cancer by suppression of NF-κB and STAT3 targeted genes such as bcl-2." (PMID 28883791, 2017). "We previously reported that pSTAT3 Ser727 is highly elevated in endometrial cancer cell lines and human samples compared to pSTAT3 Tyr705, which is the form of activated STAT3 more commonly found in STAT3-overexpressing cancers (including ovarian cancer)." (PMID 28114390, 2017). "In conclusion, our study identifies a novel molecular mechanism for E2F1, whereby it targets miR-519d to upregulate RhoC, Bcl-2, cyclin D1, survivin, MMP2, MMP9, STAT3 and HuR expression, promoting tumorigenesis and progression in ovarian carcinoma." (PMID 28146423, 2017). "Previous studies have indicated that STAT3 inhibitors, in combination with cisplatin, enhance cisplatin sensitivity in cisplatin-resistant ovarian cancer." (PMID 28691013, 2017). "We found that miR-519d transfection decreased MMP2, MMP9, STAT3, and HuR expression in ovarian carcinoma cells; at the same time, E2F1 increased the expression of these genes." (PMID 28146423, 2017). "Recent studies have shown that aberrant STAT3 activation was closely related with cell growth, cell cycle progression, invasion and drug resistance of ovarian cancer cells." (PMID 29050266, 2017). "Recent studies have shown that aberrant STAT3 activation was closely related with cell growth, cell cycle progression and invasion of ovarian cancer cells." (PMID 29050266, 2017).
ovarian carcinoma (continued). "Effective inhibition of this signaling pathway, through the use of STAT3 inhibitors, has been observed to inhibit growth and proliferation of ovarian cancer cells." (PMID 28859117, 2017). "In ovarian carcinoma tissues, activation of STAT3 correlates with expression of VEGFA, VEGFR1 and VEGFR245." (PMID 28383032, 2017). "Taken together, these results indicate that stimulation of ovarian cancer cell growth by leptin involves, at least in part, ERα transcriptional activation via STAT3 signaling pathways." (PMID 28750624, 2017). "Using epithelial ovarian cancer cell lines as in vitro model, we show an abundance of phosphorylated STAT3 at Tyr705 (p-STAT3) in SKOV3 cell line." (PMID 28859117, 2017). "This indicates that leptin can utilize multiple pathways to influence cancer cell migration, although we showed that in ovarian cancer cells inhibition of the JAK2/STAT3 pathway was sufficient to block this effect." (PMID 29212170, 2017). "Inhibition of GP130 by SC144 treatment decreased constitutive STAT3 phosphorylation and its downstream gene expression, induced apoptosis, as well as suppressed tumor growth in human ovarian cancer xenograft." (PMID 28672024, 2017). "Activation of STAT3 signaling is known to be important for the oncogenic properties of cancer cells, including ovarian cancer cells." (PMID 28859117, 2017). "Here, we demonstrate, for the very first time, constitutive activation of STAT3 in ovarian cancer cells, and that MMP-9 gene promoter contains a STAT3 DNA responsive element." (PMID 28859117, 2017). "Activation of STAT3-ERα signaling is involved in leptin-induced gene expression in ovarian cancer cells." (PMID 28750624, 2017). "This study identified leptin-induced migration of LEPR-positive ovarian cancer cells mediated via JAK2/STAT3." (PMID 29212170, 2017). "Downregulation of AXL through the IL6/STAT3 pathway resulted in overcoming taxol resistance in ovarian cancer cells." (PMID 27590506, 2016). "Collectively, our findings provide encouraging evidence of a new therapeutic target to inhibit CSCs-mediated ovarian cancer initiation and progression towards the IL-23/IL-23R/STAT3/NF-κB axis." (PMID 27738346, 2016). "To evaluate this finding in ovarian cancer patient samples, we measured total STAT3 and phosphorylated STAT3 after treatment with niclosamide." (PMID 27888804, 2016). "In this regard, activation of the IL6-Janus kinase 2 (JAK2)-STAT3 pathway has been observed in myeloproliferative disorders and ovarian cancer." (PMID 27409672, 2016). "Niclosamide reduced STAT3 and mTOR downstream protein expression in ascites cells from ovarian cancer patients." (PMID 27888804, 2016). "Taken together, these data clearly confirm a critical role for cytokine-mediated STAT3 deregulation in ovarian cancer by exerting pro-tumorigenic effects on both tumor cells and macrophages and its potential as a drug target." (PMID 27215396, 2016). "NFκB has been shown to possess a biphasic role in ovarian cancer while paclitaxel treatment of ovarian cancer cells has been reported to activate the STAT3 pathway." (PMID 26964739, 2016). "Taken together, our study emphasizes the important roles of STAT3 and NF-κB signaling pathways in ovarian cancer progression inferring to the ability of CSCs to undergo self-renewal." (PMID 27738346, 2016). "Clinical trials are evaluating mTOR inhibitors, Wnt inhibitors, and STAT3 inhibitors in ovarian cancer and other solid tumors." (PMID 27888804, 2016). "The observation that niclosamide can target the Wnt, mTOR and STAT3 pathways and reverse platinum resistance, provides compelling evidence to consider clinical studies with niclosamide in patients with ovarian cancer." (PMID 27888804, 2016). "In agreement with the established function of deregulated STAT3 in ovarian cancer, IL-10, IL-6, and LIF were confirmed as components of the signaling network established by tumor cells and TAMs." (PMID 27215396, 2016).
ovarian carcinoma (continued). "Western blot analysis of the phosphorylated (Tyr705) STAT3 protein after 24 h treatment with niclosamide (1 – 8 μM) showed a dose-response inhibition in ovarian cancer patient ascites sample OV-15." (PMID 27888804, 2016). "They suppressed LRP6 expression, inhibited both Wnt/β-catenin and mTOR/STAT3 signaling in ovarian cancer ascites cells and chemoresistant cell lines, and displayed potent in vitro anti-proliferative effects." (PMID 27888804, 2016). "Niclosamide has been shown to be anti-proliferative against prostate, colorectal, lung, breast, and ovarian cancers, and myelogenous leukemia by inhibiting multiple pathways (Wnt/β-catenin, Notch, NF-kB, mTOR, and STAT3) and inducing mitochondrial uncoupling." (PMID 27888804, 2016). "Overall, these results support a consistent synergistic effect of EGFR and JAK/STAT3 inhibition on ovarian cancer cell growth and survival both in vitro and in vivo and a potential role for multiple survival pathways in this effect." (PMID 25928246, 2015). "WP1066, a JAK2 inhibitor, suppresses ovarian cancer growth, migration, and invasion; this inhibitor also enhances the chemosensitivity of ovarian cancer cells and decreases the rate of STAT3 phosphorylation." (PMID 26631279, 2015). "The connection between JAK2/STAT3 pathway activation and CSCs has been highlighted in a previous work on ovarian cancer, where the SC marker CD44 together with the embryonic SC marker NANOG have been associated with the activation of STAT3." (PMID 26312765, 2015). "CA is an ursane-type triterpenoid, and is known to be a STAT3 inhibitor in macrophages, myeloid cells, and ovarian cancer cells." (PMID 25978354, 2015). "Because LPA activates STAT-3 in ovarian cancer cells, we decided to evaluate the participation of this transcription factor in our study model." (PMID 26418031, 2015). "We found that the transcription factors c-Myc, AP-1, and STAT3 highly upregulated their target txr genes in ovarian cancer cells." (PMID 26318424, 2015). "We here examined the sensitivity of ovarian cancer cells to gefitinib when the JAK/STAT3 pathway was depleted either with JAK1 siRNA or STAT3 siRNA." (PMID 25928246, 2015). "Activations of Wnt, Notch and STAT3 signaling are frequent in ovarian cancers/OCs and supposed to be important for OC formation and progression, while the impacts of resveratrol on these signaling pathways in OC cells remain obscure." (PMID 25896424, 2015). "Our results suggest the significance of STAT3 activation in the maintenance and survival of ovarian cancer cells." (PMID 25896424, 2015). "For instance, hyperactive Jaks/STAT3 signaling promote enhanced colony-forming ability, motility and migration of cisplatin-resistant ovarian cancer cells." (PMID 25896424, 2015). "In the present study, we found that inhibition of EGFR in ovarian cancer cells increased phosphorylation of STAT3 in both SKOV3 and MDAH2774 cells in a time- and dose-dependent manner." (PMID 25928246, 2015). "This JAKi has been shown to inhibit phosphorylation of STAT3 in various cancer cells, including human ovarian cancer cell lines MDAH2774 and SKOV3." (PMID 25928246, 2015). "We demonstrate, for the first time, that inhibition of EGFR significantly increased phosphorylation of STAT3 in ovarian cancer cells and blocking STAT3 activation led to enhanced anti-tumor activity of gefitinib both in vitro and in vivo." (PMID 25928246, 2015). "In a variation on this theme, but also involving AhR, a positive feedback loop encompassing IL-6 expression and STAT3 has recently been described in various tumor cells, including ovarian cancer." (PMID 26343197, 2015). "Relative to the other pathways considered in this study, targeting STAT3 appeared to be the most effective way to increase the therapeutic efficacy of anti-EGFR therapy in these ovarian cancer cells." (PMID 25928246, 2015).